FCN1 (ficolin 1)
Diseases named in the same sentence as FCN1 in open-access papers (continued):
Sharing a sentence is not in itself a finding about the gene and the disease.
cancer (10 papers, 2018 to 2025). A tumor composed of atypical neoplastic, often pleomorphic cells that invade other tissues. "Gene set enrichment analysis reveals significant associations between FCN1 and several pathways in pan-cancer analysis, including INFLAMMATORY_RESPONSE, INTERFERON_ALPHA_RESPONSE, INTERFERON_GAMMA_RESPONSE, ALLOGRAFT_REJECTION, and TNFA_SIGNALING_VIA_NFKB." (PMID 39139822, 2024). "Functional enrichment analysis revealed significant associations between FCN1 and multiple immune and cancer-related pathways." (PMID 39139822, 2024). "This study aims to elucidate the prognostic significance, immune signature, and treatment response associated with FCN1 across diverse cancer types." (PMID 39139822, 2024). "In this study, we comprehensively examined the clinical prognosis, immune signature, treatment response, and underlying molecular mechanisms associated with FCN1 across various cancer types, marking the first investigation of its kind." (PMID 39139822, 2024). "Apart from the notable inverse association observed with T cell recognition of cancer cells (Step 6), FCN1 exhibited a significant positive correlation with other stages, notably the recruitment of multiple immune cells during immune cell trafficking towards tumors (Step 4)." (PMID 39139822, 2024). "Initially, we found that FCN1 was significantly associated with multiple immune subtypes of cancer." (PMID 39139822, 2024). "Additionally, ROC curves hinted at FCN1’s potential as a diagnostic biomarker in select cancers." (PMID 39139822, 2024). "Integration of samples from TCGA and GTEx unveiled dysregulated FCN1 expression in 21 of 33 cancer types, particularly prominent in AML." (PMID 39139822, 2024). "Building upon these foundational studies, the current research endeavors to comprehensively examine the expression patterns, prognostic value, and functional roles of FCN1 across various cancer types, with a particular emphasis on its relevance in AML." (PMID 39139822, 2024). "CancerSEA data further corroborates these findings, demonstrating significant relationships between FCN1 and pan-cancer pathways such as Angiogenesis, Apoptosis, Differentiation, Epithelial-Mesenchymal Transition (EMT), Inflammation, and Metastasis." (PMID 39139822, 2024). "We postulate that increased FCN1 expression augments the inflammatory response within tumors, thereby facilitating antigen release and presentation by cancer cells." (PMID 39139822, 2024). "Our analysis, incorporating transcriptomics, single-cell omics, and spatial omics, identified FCN1 as a potential pan-cancer biomarker for macrophage infiltration." (PMID 39139822, 2024). "Single-cell transcriptional data sourced from TISCH corroborated the expression of FCN1 primarily in macrophages across various cancer types." (PMID 39139822, 2024). "Collectively, these findings underscore a pivotal relationship between FCN1 and genomic instability across diverse cancer types." (PMID 39139822, 2024). "Higher expression of HIF1A, ABCA1, FPR1, CD63, and FCN1 was found in cancer compared to healthy state." (PMID 39315092, 2024). "Furthermore, FCN1 expression exhibited significant associations with molecular subtypes and clinical stages across various tumors, suggesting that dysregulated FCN1 expression in diverse cancers may contribute to tumorigenesis and progression." (PMID 39139822, 2024). "Our investigation delved into the relationship between FCN1 and various stages of the cancer immune cycle." (PMID 39139822, 2024). "Conversely, pathways such as Lysine degradation and the Citrate cycle (TCA cycle) are inhibited in the FCN1 high-expression group in select cancers." (PMID 39139822, 2024). "This study presents a pioneering evaluation of FCN1’s distinct expression profiles at mRNA, transcript, and protein levels across 33 tumors, marking the first pan-cancer analysis of its kind." (PMID 39139822, 2024).
cancer (continued). "Another TAM subset, characterized by high expression of the core gene FCN1, is also identified in cancer tissues." (PMID 38347955, 2023). "Additional genes with significance or significant trends for Cancer/control group differences included FCN1 and PEMT at the intron region." (PMID 29876008, 2018). "Cancer cell line profiling revealed FCN1 expression in cancer cell lines." (PMID 39139822, 2024). "Employing multi-omics data, we conducted a comprehensive assessment, encompassing tissue-specific and single-cell-specific expression disparities, pan-cancer expression patterns, epigenetic modifications affecting FCN1 expression, and the immune microenvironment." (PMID 39139822, 2024). "Furthermore, we observed unbalanced expression of the FCN1 protein transcript in 20 cancers, with significantly elevated expression in AML and markedly reduced expression in most other cancers." (PMID 39139822, 2024). "Notably, FCN1 exhibited significantly elevated expression levels in macrophages across several cancers, including AML, BRCA, CHOL, NSCLC, PRAD, and SKCM." (PMID 39139822, 2024). "In the high-expression group of FCN1, multiple steps of the anti-cancer immune response were significantly upregulated, likely attributable to FCN1’s pro-inflammatory effects within tumors, which activate and regulate the immune system, thereby fostering an anti-cancer immune response." (PMID 39139822, 2024). "Hence, our study aims to comprehensively analyze FCN1 in pan-cancer settings from a multi-omics perspective, focusing on its expression variances, genetic alterations, immunological attributes, and predictive potential for immunotherapy." (PMID 39139822, 2024). "FCN1 expression exhibits widespread dysregulation across various cancers." (PMID 39139822, 2024). "Notably, FCN1 displayed a significant positive correlation with ips_ctla4_neg_pd1_pos and ips_ctla4_pos_pd1_pos across diverse cancer types." (PMID 39139822, 2024). "Moreover, metabolic pathways, including Glycosphingolipid biosynthesis and degradation, Tryptophan metabolism, and Arachidonic acid metabolism, are activated in the FCN1 high-expression group across multiple cancers such as BRCA, COAD, AML, and LUAD." (PMID 39139822, 2024). "Notably, FCN1 also displayed varied associations with DSS and DFI across multiple cancer types." (PMID 39139822, 2024). "By contrast, the FN1-related molecular pairs, including FN1-CD44 (a marker of cancer stem cells) and FN1-(ITGAV + ITGB1), were prompted between SELENOP-Mφ/SPP1-Mφ and FABP4-Mφ/FCN1-Mφ/CD4/CD8 cells in LUAD." (PMID 36008393, 2022). "We conducted an analysis of the correlation between FCN1 and 150 immune regulatory factors encompassing chemokines, receptors, MHC molecules, immunoinhibitors, and immunostimulators across various cancer types." (PMID 39139822, 2024).
FCN1 also shares sentences with these, for which no sentence is quoted: ischemic stroke (3 papers); acute lymphoblastic leukaemia (2); juvenile idiopathic arthritis (2); lung carcinoma (2); lupus nephritis (2); neutropenia (2); pneumococcal infection (2); AIDS (1); Airway obstruction (1); bacterial infection (1); basal cell carcinoma (1); Behcet disease (1); Cerebral ischemia (1); Chagas disease (1); chronic hepatitis C (1); colon adenocarcinoma (1); complement deficiencies (1); coronary artery disease (1); Crohn disease (1); cystic fibrosis (1); Glioblastoma multiforme (1); head and neck squamous cell carcinoma (1); hematological cancer (1); Hypertension (1); injury (1); interstitial lung disease (1); liver cirrhosis (1); liver diseases (1); liver inflammation (1); lung adenocarcinoma (1).
A further 19 diseases each share a sentence with FCN1 in 1 paper.